MED13L (mediator complex subunit 13L)
Description:
Component of the Mediator complex, a coactivator involved in the regulated transcription of nearly all RNA polymerase II-dependent genes. Mediator functions as a bridge to convey information from gene-specific regulatory proteins to the basal RNA polymerase II transcription machinery. Mediator is recruited to promoters by direct interactions with regulatory proteins and serves as a scaffold for the assembly of a functional preinitiation complex with RNA polymerase II and the general transcription factors. This subunit may specifically regulate transcription of targets of the Wnt signaling pathway and SHH signaling pathway.
Synonyms: KIAA1025; PROSIT240; THRAP2; TRAP240L; MRFACD
Tractability: PROTAC: ubiquitination databases record sites on it.
Gene: Protein-coding gene on chromosome 12 (115,957,905 to 116,277,693, reverse strand). Ensembl gene ENSG00000123066.
Subcellular location: Nucleus
Subcellular location (Human Protein Atlas): Nucleoplasm; Golgi apparatus
Pathways (Reactome):
Developmental Biology: Transcriptional regulation of white adipocyte differentiation
Disease: RSV-host interactions
Metabolism: PPARA activates gene expression
Gene Ontology:
Molecular function: transcription coactivator activity; transcription coregulator activity
Biological process: positive regulation of transcription by RNA polymerase II; regulation of transcription by RNA polymerase II
Cellular component: nucleoplasm; mediator complex; nucleus
Genetic constraint (gnomAD): Loss-of-function variants: 4 observed, 223.04 expected, observed/expected ratio (o/e) 0.0179, 90% interval 0.008 to 0.041. The upper end of that interval is the gene's LOEUF score, 0.041, which puts it in group 1 of 6, group 1 being the genes least tolerant of losing a copy. Missense variants: 1,951 observed, 2,876.1 expected, observed/expected ratio (o/e) 0.68, 90% interval 0.65 to 0.7. Synonymous variants: 1,005 observed, 1,058.9 expected, observed/expected ratio (o/e) 0.95, 90% interval 0.9 to 1.
Gene-disease validity (ClinGen):
ClinGen rates the evidence that MED13L causes each of these diseases.
syndromic intellectual disability (autosomal dominant): Definitive. A intellectual disability that is part of a larger syndrome.
congenital heart disease (autosomal dominant): Limited. A heart disease that is present at birth.
Homologues: Orthologues: chimpanzee MED13L (99% identical), macaque MED13L (99% identical), pig MED13L (97% identical), dog MED13L (97% identical), rabbit MED13L (96% identical), guinea pig MED13L (96% identical), mouse Med13l (92% identical), rat Med13l (92% identical), tropical clawed frog med13l (67% identical), Drosophila melanogaster skd (33% identical), Caenorhabditis elegans let-19 (25% identical). Paralogues in human: MED13 (53% identical).
Diseases named in the same sentence as MED13L in open-access papers:
MED13L is named in the same sentence as 45 diseases in open-access papers, as found by Europe PMC text mining. Sharing a sentence is not in itself a finding about the gene and the disease. The quoted sentences say what the papers report.
Intellectual disability (12 papers, 2015 to 2025). "MED13L-related intellectual disability is a syndromic intellectual disability caused by MED13L gene mutations inherited in an autosomal-dominant pattern." (PMID 41403746, 2025). "Haploinsufficiency of the syntenic region containing TBX3 and MED13L has been reported to cause short stature, developmental delay, and intellectual disability, among other conditions in humans, and is established as a major contributor to height in horses." (PMID 33863806, 2021). "Although the de novo stop-gain variant of MED13L p.Arg1760∗ was previously reported in an intellectual disability case, we also identified de novo variants of PPP5C and NCKAP1L in the same individual with the MED13L variant." (PMID 33748132, 2021). "In this work, we report a patient with a novel de novo likely pathogenic variant c.5941C>T, p.(Gln1981*) in the MED13L gene with severe intellectual disability and facial dysmorphism." (PMID 33930262, 2021). "Polymorphisms in the MED13L gene have been linked to congenital heart anomalies and intellectual disabilities." (PMID 29951696, 2018). "MED13L was previously associated with intellectual disability and heart defects, and a de novo splicing mutation was described in an autistic patient." (PMID 25969726, 2015). "A later study also identified conotruncal heart defects and intellectual disability in patients with haploinsufficiency of MED13L." (PMID 39257968, 2024). "In addition, we further review the literature for previously reported patients and expand the phenotypic and genetic spectrum of MED13L-related intellectual disability." (PMID 41403746, 2025). "In addition, PROSIT240 (also termed THRAP2 or MED13L) mutations have been identified in patients with D-TGA with or without intellectual disability." (PMID 39200964, 2024).
developmental delay (6 papers, 2018 to 2025). "Pathogenic variants within the MED13L gene cause MED13L syndrome (MIM #616789), described as a global developmental delay in motor and language acquisition, with ID severity ranging from mild to severe." (PMID 40389839, 2025). "Based on this database and literature, MED13L haploinsufficiency syndrome is characterised by a wide spectrum of clinical features, but almost all individuals, including our proband, have ID, psychomotor developmental delay, and speech delay." (PMID 37512036, 2023). "Indeed, with the development of sequencing (exome or genome) approaches for patients with ID or global developmental delay (GDD), MED13L appears to be one of the most frequently affected genes in series of patients with ID/GDD." (PMID 40389839, 2025).
autism (3 papers, 2018 to 2025). Persistent deficits in social interaction and communication and interaction as well as a markedly restricted repertoire of activity and interest as well as repetitive patterns of behavior. "According to the literature, missense variants in the MED13 homolog gene MED13l have been reported to correlate with more severe phenotypes, including a higher incidence of seizures, MRI abnormalities, autism spectrum features, and cardiac abnormalities." (PMID 41195223, 2025). "We found differential expression of autism-relevant genes in our DE gene list that are also associated with cell adhesion (Dscam, Reln) or gene regulation (Kat2b, Kmt2c, Med13/Med13l, Tbl1xr1, Ubn2)." (PMID 33757588, 2021). "The main phenotypic characteristics of MED13L-associated syndrome are (borderline) ID with delayed speech and language development, and a variable spectrum of other features including autism, hypotonia, characteristic facial features and heart defects." (PMID 29740699, 2018).
Asadollahi-Rauch syndrome (2 papers, 2021 to 2025). "Our findings support the conclusion that the phenotype of patients with loss-of-function variants in the MED13L gene could be a clinically recognizable MRFACD syndrome, especially when ID is accompanied by development and speech delay and specific dysmorphic features." (PMID 33930262, 2021).
leukemia (2 papers, 2021 to 2023). A malignant (clonal) hematologic disorder, involving hematopoietic stem cells and characterized by the presence of primitive or atypical myeloid or lymphoid cells in the bone marrow and the blood. "Other key leukemia-specific hits include MYB, MED13L, HOXA10, and the binding partner of RUNX1, CBFB." (PMID 34088716, 2021).
autoimmune disease (1 paper, 2018). A disorder resulting from loss of function or tissue destruction of an organ or multiple organs, arising from humoral or cellular immune responses of the individual to their own tissue constituents. "We used BR.RIIIS/J-Eae39r1 congenic mice that express the Med13L gene from the CIA and EAE resistant RIIIS/J donor strain on the genetic background of the B10.RIII, which is susceptible to the experimental autoimmune disease models." (PMID 29951696, 2018). "Despite these reports on a potential role of MED13L in immune function and inflammation, the effect of genetic variations in this gene has not been studied in immune cells and animal models of autoimmune diseases." (PMID 29951696, 2018).
Autoimmunity (1 paper, 2018). The occurrence of an immune reaction against the organism's own cells or tissues. "Considering the putative role of Med13L in autoimmunity, we studied the in vivo effect of the identified Med13L SNPs in the CIA mouse model." (PMID 29951696, 2018). "However, the role for Med13L in other inflammation- and autoimmunity-related pathways warrants further investigation." (PMID 29951696, 2018).
Coffin-Siris syndrome (1 paper, 2018). Coffin-Siris syndrome (CSS) is a rare congenital multi-systemic genetic disorder characterized by aplasia or hypoplasia of the distal phalanx or nail of the fifth digit, developmental delay, intellectual disability, coarse facial features, and other variable clinical manifestations. "MED13L and Coffin-Siris syndrome were never discussed as differential diagnosis to each other but our experience expands the known MED13L spectrum and suggests a previously unrecognized clinical overlap." (PMID 30091983, 2018).
colon cancer (1 paper, 2020). "On the contrary, in colon cancer, simultaneous depletion of MED13L and MED13 led to decreased cell viability 36 and supported the oncogenic functions of MED13L, which is consistent to our findings in NSCLC." (PMID 32802198, 2020).
Cornelia de Lange syndrome (1 paper, 2023). A rare syndrome characterized by low birth weight, delayed growth, intellectual disabillity, behavioral problems, and a distinctive facial appearance (thin, arched eyebrows, low set ears, small teeth, and small nose). "Some recent studies demonstrated that the pathogenic variants in the MED13L (MIM #608771) gene, which is located on chromosome 12 (12q24.21), can be associated with Cornelia de Lange syndrome (CdLS) or CdLS-like phenotypes." (PMID 37512036, 2023).
development (1 paper, 2023). "The pathogenic variants in MED13L present in patient AUT23 are associated with impaired intellectual development and distinctive facial features with or without cardiac defects (OMIM #616789)." (PMID 38003033, 2023).
glioblastoma (1 paper, 2020). The most malignant astrocytic tumor (WHO grade IV). "Glioblastoma T98G cells stably expressing shRNAs of MED13L conferred resistance to the proliferation arrest induced by active Rb expression and showed remarkably stronger clonogenicity compared to the control cells." (PMID 32802198, 2020).
microphthalmia (1 paper, 2023). Congenital or developmental anomaly in which the eyeballs are abnormally small. "A similar search of DR17 using the term microphthalmia resulted in 22 genes significant for the small eyes phenotype: Aldh1a3, Aff4, Bmp4, Cdk4, Cox6b1, Cxcr4, Dync1li1, Eef1d, Fgd1, Gne, Grh12, Mab21l2, Maf, Med13l, Mllt10, Mthfd2, Pex6, Phgdh, Ssr1, Stim1, Tdo2, and Vps26c." (PMID 36737727, 2023).
schizophrenia (1 paper, 2013). A major psychotic disorder characterized by abnormalities in the perception or expression of reality. "Recently MED13L has been associated with risk for schizophrenia." (PMID 23966865, 2013).
Talipes equinovarus (1 paper, 2020). Talipes equinovarus (also called clubfoot) typically has four main components: inversion and adduction of the forefoot; inversion of the heel and hindfoot; equinus (limitation of extension) of the ankle and subtalar joint; and internal rotation of the leg. "Additionally, a de novo 12q24.2 microdeletion of 392 kb was detected in foetus 36 with unilateral moderate ventriculomegaly and talipes equinovarus, encompassing exons 24–31 of mediator of RNA polymerase II transcription subunit 13-like (MED13L) gene (OMIM: 608771)." (PMID 33247184, 2020).
type 1 diabetes (1 paper, 2025). "Moreover, GWAS studies have revealed that a region proximal to the MED13L gene is associated with type 1 diabetes, a condition closely linked to MI." (PMID 40089108, 2025).
neurodevelopmental disorder (5 papers, 2015 to 2021). A behavioral and cognitive disorder with onset during the developmental period that involves impaired or aberrant development of intellectual, motor, or social functions. "A previous study reported that variants in MED12 and MED13L were associated with neurodevelopmental disorders." (PMID 33748132, 2021). "It is of particular relevance to this study that variation in the MED13-paralog MED13L has been shown to cause a neurodevelopmental disorder as well." (PMID 29740699, 2018). "Our findings are consistent with a role of MED13L in neurodevelopmental disorders." (PMID 25969726, 2015).
cancer (2 papers, 2018 to 2025). A tumor composed of atypical neoplastic, often pleomorphic cells that invade other tissues. "Additional genes identified included GALNT10, NPIPB4, POGZ, MED13L and UGGT1, most of which had confirmed roles in cancers." (PMID 40507918, 2025).
tumor (2 papers, 2020 to 2021). "While there is no significantly different level of MED13L mRNA expression level between NSCLC tumor samples and matched normal tissues." (PMID 33593390, 2021).
cardiovascular diseases (1 paper, 2020). "For instance, recent findings have shown that the Med13l gene is associated with cardiovascular diseases and that the Med subunit modifies glucose and lipid metabolism." (PMID 33224944, 2020).
genetic disorder (1 paper, 2021). "MRFACD is a genetic disorder caused by molecular defect of the MED13L gene." (PMID 33930262, 2021).
heart (1 paper, 2021). "Intriguingly, many mutations in MED13L are found in its IDR and result in a haplo-insufficiency syndrome characterized by a spectrum of symptoms including congenital heart and intellectual disorders." (PMID 34683473, 2021).
MED13L also shares sentences with these, for which no sentence is quoted: congenital heart defects (2 papers); neurological disorders (2); Arthritis (1); Ataxia (1); breast carcinoma (1); colorectal cancer (1); Dyskinesia (1); Dystonia (1); end stage renal disease (1); epilepsy (1); experimental arthritis (1); hyperthyroidism (1); Impaired glucose tolerance (1); lung carcinoma (1); Myoclonus (1); non-small cell lung carcinoma (1); Obesity (1); renal hypoplasia (1); speech delay (1); Tremor (1); unspecified (1); Ventriculomegaly (1); vesicoureteral reflux (1).